ZBTB17 (zinc finger and BTB domain containing 17)
Description:
Transcription factor that can function as an activator or repressor depending on its binding partners, and by targeting negative regulators of cell cycle progression. Plays a critical role in early lymphocyte development, where it is essential to prevent apoptosis in lymphoid precursors, allowing them to survive in response to IL7 and undergo proper lineage commitment. Has been shown to bind to the promoters of adenovirus major late protein and cyclin D1 and activate transcription. Required for early embryonic development during gastrulation. Represses RB1 transcription; this repression can be blocked by interaction with ZBTB49 isoform 3/ZNF509S1.
Synonyms: Miz-1; MIZ1; ZNF151; ZNF60; pHZ-67
Tractability: Small molecule: it has a high-quality binding pocket. PROTAC: UniProt records ubiquitination sites on it; ubiquitination databases record sites on it.
Target class: Transcription factor
Gene: Protein-coding gene on chromosome 1 (15,940,403 to 15,976,132, reverse strand). Ensembl gene ENSG00000116809.
Subcellular location: Nucleus
Pathways (Reactome):
Cellular responses to stimuli: XBP1(S) activates chaperone genes
Gene Ontology:
Molecular function: core promoter sequence-specific DNA binding; DNA-binding transcription activator activity, RNA polymerase II-specific; DNA-binding transcription factor activity; DNA-binding transcription factor binding; protein binding; RNA polymerase II cis-regulatory region sequence-specific DNA binding; transcription coactivator binding; DNA-binding transcription repressor activity, RNA polymerase II-specific; DNA binding
Biological process: G1 to G0 transition; negative regulation of cell population proliferation; positive regulation of transcription by RNA polymerase II; negative regulation of cell cycle; negative regulation of transcription by RNA polymerase II; regulation of cytokine production; regulation of immune system process; positive regulation of DNA-templated transcription
Cellular component: protein-containing complex; protein-DNA complex; nucleoplasm; nucleus
Genetic constraint (gnomAD): Loss-of-function variants: 24 observed, 76.58 expected, observed/expected ratio (o/e) 0.31, 90% interval 0.23 to 0.44. The upper end of that interval is the gene's LOEUF score, 0.44, which puts it in group 1 of 6, group 1 being the genes least tolerant of losing a copy. Missense variants: 743 observed, 1,066.7 expected, observed/expected ratio (o/e) 0.7, 90% interval 0.65 to 0.74. Synonymous variants: 464 observed, 456.76 expected, observed/expected ratio (o/e) 1.02, 90% interval 0.94 to 1.1.
Homologues: Orthologues: chimpanzee ZBTB17 (99% identical), macaque ZBTB17 (99% identical), pig ZBTB17 (94% identical), rabbit ZBTB17 (94% identical), dog ZBTB17 (93% identical), guinea pig ZBTB17 (92% identical), mouse Zbtb17 (92% identical), rat Zbtb17 (92% identical), tropical clawed frog zbtb17 (69% identical), zebrafish zbtb17 (59% identical). Paralogues in human: ZKSCAN7 (22% identical), ZNF852 (21% identical), ZNF287 (21% identical), ZNF34 (21% identical), ZNF527 (21% identical), ZNF407 (20% identical), ZNF214 (20% identical), ZNF136 (20% identical), ZNF285 (20% identical), ZNF572 (20% identical), ZNF17 (20% identical), ZNF416 (19% identical), and 38 more.
Diseases named in the same sentence as ZBTB17 in open-access papers:
ZBTB17 is named in the same sentence as 20 diseases in open-access papers, as found by Europe PMC text mining. Sharing a sentence is not in itself a finding about the gene and the disease. The quoted sentences say what the papers report.
Alzheimer disease (1 paper, 2024). A progressive, neurodegenerative disease characterized by loss of function and death of nerve cells in several areas of the brain leading to loss of cognitive function such as memory and language. "Our CRISPR‐based study highlights the therapeutic potential of targeting NKRF and ZBTB17 expressions to manage Alzheimer's disease (AD) and atherosclerosis (AS)." (PMID 38738952, 2024). "Therefore, we speculate that NKRF and ZBTB17 may regulate the progression of Alzheimer's disease (AD) and atherosclerosis (AS) by modulating NF‐κB and its related signaling pathways in microglia and macrophages." (PMID 38738952, 2024). "Our study reveals common molecular pathways in Alzheimer's disease (AD) and atherosclerosis (AS), notably in genes like BEX2, NKRF, SOD1, UBL5, ZBTB17, and ZNHIT3." (PMID 38738952, 2024). "The results of the analysis demonstrated significant inhibition in the progression of Alzheimer's disease (AD) in NKRF knock‐in (NKRF) and ZBTB17 knockout (ZBTB17−/−) mice compared to the model mice (3×Tg and 3×Tg/ApoE−/− + HFD)." (PMID 38738952, 2024).
chronic obstructive pulmonary disease (1 paper, 2023). A chronic and progressive lung disorder characterized by the loss of elasticity of the bronchial tree and the air sacs, destruction of the air sacs wall, thickening of the bronchial wall, and mucous accumulation in the bronchial tree. "Myc-interacting zinc finger protein-1 (Miz1, also named ZBTB17) protein levels are decreased in the lung epithelial cells of patients with severe chronic obstructive pulmonary disease." (PMID 37608279, 2023).
clear cell renal cell carcinoma (1 paper, 2022). "A search against COSMIC identified a number of mutations found in tumors (i.e. adenocarcinoma, squamous cell carcinoma, malignant melanoma and clear cell renal cell carcinoma) localizing within fragments corresponding to SPATA22, ZBTB17, CCT7, MAP1S and PDIA3 proteins." (PMID 35205757, 2022).
Eμ- (1 paper, 2017). "In 3T9MYC-ER cells and Eμ-myc lymphomas, instead, the MYC share had much stronger predictive values, with minor albeit significant contributions of ZBTB17—whether expressed as a MYC/ZBTB17 ratio or as straight ZBTB17 binding." (PMID 28904013, 2017).
gastric cancer (1 paper, 2023). A primary or metastatic malignant neoplasm involving the stomach. "A targeted proteomics approach has revealed ZBTB17 serves as a diagnostic marker for resectable gastric cancer." (PMID 37466419, 2023).
liver neoplasm (1 paper, 2025). Tumors or cancers of the LIVER. "The ‘liver neoplasms’ CTD over-representation could be attributed to cell cycle-related pathway enrichment and corresponding genes (cell cycle: PDS5A, ORC6, RAD21, ZBTB17; Thyroid cancer: CTNNB1, RET) identified from our CRIPSR screens." (PMID 41446233, 2025).
oligodendroglioma (1 paper, 2018). A well-differentiated (WHO grade II), diffusely infiltrating neuroglial tumor, typically located in the cerebral hemispheres. "Many of these candidates (e.g. ELTD1, SDHB, SEPW1, SLC17A7, SZRD1, THAP3, ZBTB17) are likely to push, whereas others (e.g. CAP1, HBXIP, KLK6, PARK7, PTAFR) might counteract oligodendroglioma development." (PMID 29890994, 2018). "Interestingly, several of these genes (e.g. ELTD1, SDHB, SEPW1, SLC17A7, SZRD1, THAP3, ZBTB17) are likely to push, whereas other genes (e.g. CAP1, HBXIP, KLK6, PARK7, PTAFR) might restrict oligodendroglioma development." (PMID 29890994, 2018).
small cell lung carcinoma (1 paper, 2024). Small cell lung cancer (SCLC) is a highly aggressive malignant neoplasm, accounting for 10-15% of lung cancer cases, characterized byrapid growth, and early metastasis. "Both ZBTB17 and PTEN are part of the WP_SMALL_CELL_LUNG_CANCER pathway, indicating their relevance to small cell lung cancer." (PMID 38867699, 2024).
tumor (4 papers, 2016 to 2024). "Further reinforcing this progression, Myc also represses other transcription factors that activate genes involved in tumor suppression, including Myc-interacting zinc finger protein-1, (Miz1, also known as Pias2 and ZBTB17)." (PMID 32059473, 2020).
cancer (1 paper, 2024). A tumor composed of atypical neoplastic, often pleomorphic cells that invade other tissues. "Heterogeneous graph nodes and paths judging the top 10 contributions of ZBTB17 as a cancer driver gene." (PMID 38867699, 2024). "Hence, it is reasonable to believe that PTEN is a cancer driver gene that interacts or mutually influences ZBTB17 gene." (PMID 38867699, 2024). "We will illustrate how MCDHGN demonstrates biological interpretability in predicting cancer driver genes by presenting case studies on the SETD2 and ZBTB17 genes." (PMID 38867699, 2024).
ZBTB17 also shares sentences with these, for which no sentence is quoted: adenocarcinoma (1 paper); atherosclerosis (1); bladder cancer (1); diabetes (1); idiopathic dilated cardiomyopathy (1); malignant melanoma (1); peroxisome biogenesis disorder (1); rectal cancer (1); squamous cell carcinoma (1); thyroid cancer (1).